CST9 (cystatin 9)
Description:
May be involved in testis development (By similarity). May play a role in hematopoietic differentiation or inflammation. Has immunomodulatory and antimicrobial functions against Francisella tularensis, a Gram-negative bacteria.
Synonyms: CLM; CTES7A
Tractability: Antibody: UniProt places it where antibodies can reach, with high confidence; UniProt predicts a signal peptide or a membrane-spanning region; its Gene Ontology location is reachable by antibodies, with medium confidence.
Gene: Protein-coding gene on chromosome 20 (23,602,410 to 23,605,917, reverse strand). Ensembl gene ENSG00000173335.
Subcellular location: Secreted
Gene Ontology:
Biological process: antimicrobial humoral response
Cellular component: extracellular region
Genetic constraint (gnomAD): Loss-of-function variants: 11 observed, 8.32 expected, observed/expected ratio (o/e) 1.32, 90% interval 0.82 to 1.88. That is too few expected variants to judge how well the gene tolerates losing a copy. Missense variants: 214 observed, 209.16 expected, observed/expected ratio (o/e) 1.02, 90% interval 0.91 to 1.15. Synonymous variants: 71 observed, 78.4 expected, observed/expected ratio (o/e) 0.91, 90% interval 0.75 to 1.1.
Homologues: Orthologues: chimpanzee CST9 (96% identical), macaque CST9 (96% identical), zebrafish si:busm1-57f23.1 (11% identical), Caenorhabditis elegans cpi-2 (8% identical), Caenorhabditis elegans cpi-1 (8% identical), Caenorhabditis elegans K08B4.7 (5% identical). Paralogues in human: CST9L (40% identical), CST1 (19% identical), CST2 (18% identical), CST4 (18% identical), CST3 (18% identical), CST5 (18% identical), CST11 (14% identical), CST6 (14% identical), CST7 (14% identical), CST8 (14% identical), CSTL1 (14% identical).
Diseases named in the same sentence as CST9 in open-access papers:
CST9 is named in the same sentence as 6 diseases in open-access papers, as found by Europe PMC text mining. Sharing a sentence is not in itself a finding about the gene and the disease. The quoted sentences say what the papers report.
cyst (2 papers, 2020 to 2025). A sac-like closed membranous structure that may be empty or contain fluid or amorphous material. "In contrast, higher levels of anti-BCLA and anti-CST9 IgG were more predictably associated with brain lesions linked to cyst formation." (PMID 41346605, 2025). "Conversely, higher anti-BCLA and anti-CST9 responses correlate with tissue cyst burden and lesion severity." (PMID 41346605, 2025). "After generating the deletion and complementation strains for CST4, CST8, CST9, and MCP3, these parasites were assayed for parasite and cyst biology." (PMID 32019789, 2020). "IFA showed that cyst wall proteins CST4, CST8, CST9, and MCP3 were successfully knocked out and complemented back." (PMID 32019789, 2020). "Due to their cyst wall localizations, TgME49_258870, TgME49_204340, and TgME49_310790 were renamed CST7, CST8, and CST9, respectively." (PMID 32019789, 2020). "Since only CST2-BirA*, CST4-BirA*, CST9-BirA*, and MCP3-BirA* parasites showed biotin ligase activity at the cyst wall, streptavidin affinity capture of the potential interacting partners of these cyst wall strains was performed and processed by LC-MS/MS." (PMID 32019789, 2020). "While CST4, CST8, and CST9 do not seem to play a role in determining cyst size, a lack of MCP3 resulted in statistically smaller cysts." (PMID 32019789, 2020). "When no exogenous biotin was provided, CST2-BirA*, CST4-BirA*, CST9-BirA*, and MCP3-BirA* strains showed no increase in streptavidin signal at the cyst wall." (PMID 32019789, 2020).
chronic kidney disease (1 paper, 2019). Impairment of the renal function secondary to chronic kidney damage persisting for three or more months. "For instance, rs911119 located in the CST3/CST4/CST9 gene cluster was reported previously associated with chronic kidney disease in a European population." (PMID 30704471, 2019).
male infertility (1 paper, 2024). The inability of the male to effect fertilization of an ovum after a specified period of unprotected intercourse. "Mice lacking 8 cystatin genes (Cstl1, Cst11, Cstdc1, Cst12, Cst8, Cst13, Cst9, and Cstdc2) on chromosome 2 possess defective sperm maturation and male infertility." (PMID 38169386, 2024).
infection (2 papers, 2018 to 2022). The state of being infected such as from the introduction of a foreign agent such as serum, vaccine, antigenic substance or organism. "CST9 has immune-modulatory effects such as regulating cytokine secretion and immune cell migration in inflammation and infection status." (PMID 36552753, 2022). "On the contrary, using transgenic plants silencing the cystatin-9 gene observed a reduced infection by U. maydis, but they argued that this PhyCys suppresses host immunity by inhibition of apoplastic cysteine proteases." (PMID 30522452, 2018). "Maize plants silencing the cystatin-9 gene had a reduced infection by Ustilago maydis, indicating that this PhyCys suppresses host immunity by inhibition of apoplastic cysteine proteases." (PMID 30522452, 2018).
cancer (1 paper, 2024). A tumor composed of atypical neoplastic, often pleomorphic cells that invade other tissues. "The other four genes, COCH, CST9, SOX11, and TDGF1, as well as CHST4, have also been implicated in the immune-related GO term, indicating the importance of immunomodulatory mechanisms in cancer therapy." (PMID 38396947, 2024).
CST9 also shares sentences with these, for which no sentence is quoted: Auditory hallucination (1 paper).